TNF (tumor necrosis factor)
Diseases named in the same sentence as TNF in open-access papers (continued):
Sharing a sentence is not in itself a finding about the gene and the disease.
autoimmune disease (continued). "In the context of the data presented here, the reduced disease severity in autoimmune diseases could be due to drug-induced neutropenia or to decreased TNF-α/IL-6 levels from antibody treatment." (PMID 33986193, 2021). "Biological and Kyoto Encyclopedia of Genes and Genomes (KEGG) pathway analyses showed that PAUF is associated with IL-8, nitric oxide biosynthesis, Toll-like receptor (TLR) signaling, and TNF-α processes, which are responsible for inflammatory and autoimmune diseases." (PMID 33731895, 2021). "Th1 cells secrete IL-2, INF-γ, and TNF-α; these can stimulate B lymphocytes to produce a large number of autoantibodies and induce the production of TGF-β, thus making the body susceptible to autoimmune diseases." (PMID 32565866, 2020). "Despite these apparent benefits, TNF-α inhibitors can increase the risk of demyelinating and non-demyelinating inflammatory CNS events in patients being treated for autoimmune diseases." (PMID 33233734, 2020). "TNF-α is a key cytokine in viral diseases and various chronic inflammatory and autoimmune diseases." (PMID 33147850, 2020). "TNF-alpha plays a role in the pathogenesis of autoimmune diseases, including thyroid diseases." (PMID 33042019, 2020). "Since then, the published experience with biologics during pregnancy mainly deals with the use of TNFα inhibitors (TNFα-i); data from a growing number of publications on the use of TNFα-i pregnant women with most autoimmune diseases is reassuring." (PMID 33551814, 2020). "Moreover, ADT has been revealed to reduce Th1 and Th17 responses and also the concentration of inflammatory cytokines involved in several autoimmune diseases, including IL-1β, IL-2, tumor necrosis factor (TNF)-α and interferon (IFN)-γ." (PMID 32580478, 2020). "In addition, the other genes listed include PSMD14 and TNFRSF12A, which are related to key targets in the TNF pathway of autoimmune diseases." (PMID 33299893, 2020). "We hypothesized that TNF inhibitors may further dysregulate already aberrant immune responses, triggering inflammatory CNS events in patients with certain autoimmune diseases." (PMID 32421186, 2020). "One hypothesis involves the inverse and interdependent relationship between TNF-α and interferon levels (both α and γ) and the role of increased interferon in the development of autoimmune diseases." (PMID 32337619, 2020). "Therefore, there should be caution against acute toxoplasmosis before anti-TNF therapy in autoimmune diseases." (PMID 32802484, 2020). "The TNF signalling pathway plays a crucial role in inflammatory and autoimmune diseases." (PMID 32164735, 2020). "One hypothesis is that there may be an increased expression of serum B cell-activating factor (BAFF), a tumor necrosis factor (TNF)-α family member required for B cell survival that has been documented in certain autoimmune diseases and hepatitis C infection." (PMID 32033102, 2020). "Omega-3 fatty acids present with anti-inflammatory and immunomodulatory effects and might be potential therapeutic agents for inflammatory and autoimmune diseases through decreasing the levels of C-reactive protein, IL-6, and TNF-α." (PMID 32423112, 2020). "In addition, adipocytes secrete various cytokines, such as leptin, adiponectin, IL-6, resistin, visfatin and TNF-α, which regulate the proliferation and differentiation of T cells and are involved in many chronic inflammatory and autoimmune diseases." (PMID 33329579, 2020). "We and others reported that downregulation of certain spliceosome components promotes circRNA formation over canonical mRNA splicing; and that proinflammatory cytokine TNF-a, inflammation, autoimmune disease, and tumors modulate alternative splicing and spliceosome." (PMID 31057422, 2019). "Likewise, the anti-TNF-α treatment decreases periodontal indices and TNF-α levels in the GCF of patients with both autoimmune disease and periodontitis." (PMID 31540277, 2019).
autoimmune disease (continued). "TNF-α has a central role in pathogenesis of several inflammatory and autoimmune diseases." (PMID 31824900, 2019). "During follow-up, nine of the patients were at some time exposed to NSAIDs, and eight were treated by Etanercept, a BL that treats autoimmune diseases by interfering with tumor necrosis factor (TNF) (a soluble inflammatory cytokine) by acting as a TNF inhibitor." (PMID 30944880, 2019). "TNFα inhibitor therapy is important to treat many autoimmune diseases." (PMID 30631042, 2019). "In addition, administration of anti-TNF-α antibodies was able to abrogate mercuric chloride-induced lupus-like autoimmune disease in rats." (PMID 31133860, 2019). "Etanercept can ameliorate autoimmune diseases by acting as a TNF-α inhibitor." (PMID 31847135, 2019). "Moreover, TNF-α antagonist treatment in subjects affected by autoimmune diseases improves insulin sensitivity." (PMID 31824900, 2019). "Furthermore, in the recent decade, biological agents, such as TNF-α inhibitors, have provided another effective and safe treatment options for various autoimmune diseases, including JIA, but their expensive costs have limited their application." (PMID 31443722, 2019). "TNF-α is one of the major contributors to inflammation in autoimmune diseases." (PMID 30774656, 2019). "Here, we hypothesized a role for IRF5, since this transcription factor is known to be involved in enhancing TNF transcription, is highly expressed in human myeloid APCs, and since IRF5 polymorphisms are a known risk factor for several autoimmune diseases." (PMID 31024565, 2019). "Tumor necrosis factor (TNF) inhibitors are used for treatment of different autoimmune diseases." (PMID 31700711, 2019). "Targeting TNFα as a potential HD treatment received further credence from the accessibility of the TNFα signalling inhibitor, etanercept, which is currently the treatment of choice for a number of autoimmune diseases." (PMID 31076648, 2019). "There are a number of causative agents, such as oxidative stress; metabolic disorders; genetic factors; ER stress; dysregulation of production of cytokines, such as ILs, IFNs, and TNFα; and auto reactive T-cells; all of these are the hallmarks of autoimmune diseases." (PMID 29928282, 2018). "Besides its role in human autoimmune diseases, TNFα plays an important role in the control of infectious diseases such as tuberculosis or leishmaniasis." (PMID 30108591, 2018). "TNF-α is an inflammatory cytokine that is produced by intrathyroidal inflammatory cells and thyroid follicular cells and plays a pivotal role in regulating immunological reactions and the development of autoimmune diseases." (PMID 29440561, 2018). "Moreover, pro-inflammatory cytokines, such as TNF-α and IL-6, play crucial roles in the development of inflammatory diseases and are involved in the innate immunity and autoimmune diseases." (PMID 30002289, 2018). "In addition, exacerbations of autoimmune diseases under anti-TNF therapy were attributed to anti-inflammatory effects of TNF." (PMID 29494692, 2018). "Depending on the particular autoimmune disease and stage of development, type I IFNs can promote disease through chemokine expression and antigen presentation or protect against damage through regulation of proinflammatory cytokines, including IL-1β and TNF-α." (PMID 29559569, 2018). "It is able to block human TNF (hTNF) activities both in vitro and in vivo and may be considered as a prototype of a theranostic agent for autoimmune diseases." (PMID 31544893, 2018). "Those miRNAs were involved in various pathways such as NF-κB pathways, TNF pathways, Toll-like receptor pathways which were closely related with the pathogenesis of GD and were reported in previous literatures to be related with autoimmune diseases." (PMID 29976201, 2018).
autoimmune disease (continued). "Although BCG induction of TNF can interact with both TNFR1 and TNFR2, it may induce TNF production at low levels, thereby possibly boosting the expansion of Tregs, which can provide benefits for the treatment of autoimmune diseases." (PMID 29725328, 2018). "However, there have been several investigations suggesting an anti-inflammatory role of TNF in limiting inflammatory processes induced by in vivo infections as well as by autoimmune diseases." (PMID 29494692, 2018). "This may help to further elucidate the therapeutic value of TNFα in the treatment of MS and other autoimmune diseases." (PMID 29760711, 2018). "Thus, drugs that block or reduce TNF-α activity have been developed to treat autoimmune diseases, such as RA, inflammatory bowel diseases, psoriasis, ankylosing spondylitis, and others." (PMID 29541073, 2018). "Thus, in future experimentation, it will be also interesting to see if the trimeric and dimeric TNF blockers can have a synergistic effect in blocking TNF signaling in both animal models and in the clinic for treating autoimmune diseases." (PMID 29743640, 2018). "The usage of anti-TNF antibodies or agents that block the TNF-R, such as infliximab and etanercept, can inhibit TNF-induced NF-κB activation and can have benefits in various autoimmune diseases." (PMID 30060453, 2018). "Prospectively, parts of the whole THP molecule may be used for anti-TNF-α therapy in inflammatory diseases, autoantibody-depleting therapy in autoimmune disorders, and immune intensification in immunocompromised hosts." (PMID 29361765, 2018). "Moreover, new onset or exacerbation of chronic inflammatory and autoimmune diseases has been observed in patients treated with anti-TNF therapies." (PMID 29593717, 2018). "IL-6 participates in autoimmune diseases such as hepatitis and multiple sclerosis, the secretion of which could be induced by TNF-α." (PMID 30057554, 2018). "Currently, five anti-TNF biologics have been approved for patients with autoimmune disorders." (PMID 28785220, 2017). "Tumor necrosis factor α (TNFα) is a potent pro-inflammatory cytokine that exerts pleiotropic effects on various cell types and plays a critical role in the pathogenesis of chronic inflammation and autoimmunity diseases." (PMID 28542350, 2017). "Furthermore, the polymorphism of tumor necrosis factor receptor superfamily member 1B, a gene encoding TNFR2 protein, is able to predict responses of patients with autoimmune diseases to anti-TNF therapy." (PMID 28785220, 2017). "Thus, pregnant women with autoimmune diseases and in need of anti-TNF therapy can be treated with certolizumab pegol, since polyethylene glycol does not cross the placenta." (PMID 28358311, 2017). "Paradoxically, some new autoimmune diseases can be de novo induced by anti-TNF therapy." (PMID 28785220, 2017). "Finally, our efforts were focused on the prodomain of TACE mainly because TACE was found to be a major sheddase of the pro-inflammatory cytokine TNFα that is mostly related to autoimmune disorders." (PMID 27982031, 2016). "Moreover, some therapies used in autoimmune diseases, such as tumor necrosis factor (TNF) blockers, eventually interact with the development of tumors, even though clinical studies on this topic showed discordant results." (PMID 27323400, 2016). "Similarly, in a review of published reports of autoimmune diseases that developed while taking TNFα targeted therapy, 118 cases of vasculitis were found among 379 diagnoses of a new autoimmune disease." (PMID 27529048, 2016). "Given the importance of TNF-α and IL-6 in the pathogenesis of autoimmune disease, we infer that MS might also exert a protective effect on RA and SLE." (PMID 27405597, 2016). "TNF-α plays an important role in the pathogenesis of autoimmune diseases." (PMID 27652081, 2016). "Therefore, understanding function of TNFα in autoimmune diseases and developing affordable, safe, and equally potent anti-TNFα analogues is still ongoing worldwide." (PMID 26977076, 2016).
autoimmune disease (continued). "Interestingly, while IL-1 blockade was considered less superior than TNF-α blockade in treating RA and other autoimmune diseases, it was remarkably effective in treating autoinflammatory diseases." (PMID 27070121, 2016). "Chimeric antibodies with the antigen‐binding region kept xenogenic, targeting self‐antigens are presently used successfully to treat cancer (anti‐CD20/rituximab), graft‐versus‐host disease (anti‐CD25/basiliximab), and various autoimmune diseases (anti‐TNF [tumor necrosis factor]/infliximab)." (PMID 27474782, 2016). "Anti-TNF-α therapy in human autoimmune diseases may therefore differentially affect the function of nTregs." (PMID 26834751, 2016). "However, following the successful data in the TNFα dependent autoimmune disease mice models, testing other TACE involved pathological states is a rational step." (PMID 27982031, 2016). "It is possible that in autoimmune diseases like RA, IL-6 may induce Tcon cells to resist Treg suppression, while TNFα acts on the other side of the equation to further prevent Tregs from suppressing Tcon cells." (PMID 27242798, 2016). "Th17 cells could produce IL-17, TNF-α, and IL-6 and induce inflammation in the pathogenesis of autoimmune diseases." (PMID 27777959, 2016). "The molecular basis of the association of UBE2L3 with numerous autoimmune diseases is mediated through the direct and measurable effect of the UBE2L3 autoimmune risk haplotype on NF-κB both basally and in response to TNF and CD40L stimulation in primary human monocytes and B cells, respectively." (PMID 25640675, 2015). "Indeed, the occurrence of autoimmune diseases related to anti-TNF agents, such as “lupus-like” syndrome and vasculitis, is well known with such therapy." (PMID 26425632, 2015). "In patients with autoimmune disease, frequent increased levels of pro-inflammatory cytokines (TNF-α, IL-1, IFN-γ) may result in aberrant activation of the innate immune response." (PMID 24410812, 2014). "Furthermore, TNFα is important in host resistance to TB, as evidenced by studies following anti-TNFα therapy for autoimmune disease, where patients with LTBI have been observed to develop active TB." (PMID 24715893, 2014). "One favored hypothesis of mechanism for corneal ulceration in patients with RA stems from an abnormal B and T cell interaction and increased cytokine production, specifically tumor necrosis factor (TNF) and interleukin-6 (IL-6), seen in autoimmune disease." (PMID 25031879, 2014). "Granulomatous lung disease can be caused by various agents such as interferon-γ therapy for chronic hepatitis or multiple sclerosis; methotrexate or TNF-α blocking agent for autoimmune disease; BCG; and some antineoplastic drugs including everolimus or gefitinib." (PMID 24716039, 2014). "Elevated TNF-α in the etanercept treated patients does not appear to be a significant risk factor for the spontaneous development of further autoimmune diseases in our study group." (PMID 24783218, 2014). "This may explain the correlation between serum CRT levels and autoimmune disorders, since TNF-α and IL-6 represent predominant inflammatory cytokines released by activated macrophages." (PMID 24566135, 2014). "However, during T cell mediated autoimmunity TNF-α as a Th1 cytokine exacerbates the evolvement of autoimmune diseases like T1DM." (PMID 24693923, 2014). "These contrasting effects of TNFα on effector versus regulatory T cells may explain unexpected and disappointing results obtained with anti-TNF in some autoimmune diseases such as multiple sclerosis." (PMID 24757282, 2014). "In addition to the involvement of TNF/TNF1 in autoimmune disease and malignancy, mouse models highlighted the role of this receptor ligand-system in the immune system." (PMID 23852022, 2013). "Interestingly, therapeutical agents commonly used in sarcoidosis, such as glucocorticosteroids and anti-TNF agents, interfere with granuloma integrity and restore the immune homeostasis in autoimmune disorders." (PMID 24339826, 2013).
autoimmune disease (continued). "In patients with autoimmune disease, often increased levels of proinflammatory cytokines (TNF-α, IL-1, IFN-γ) may result aberrant activation of the innate immune response." (PMID 23889805, 2013). "This speculation is also supported by the previous reports that IFN-α,IFN-β and TNF-α are involved in the pathogenesis of autoimmune diseases and that elevated TNF-α plays an essential role in the progression of liver injury." (PMID 23799121, 2013). "This is underscored by the clinical association between HIV and TB and by the increased risk to develop reactivation TB of individuals treated with anti-TNF-α agents used for a range of inflammatory/autoimmune diseases, such as rheumatoid arthritis and Crohn’s disease." (PMID 24146869, 2013). "TNF-α is an important immune cytokine involved in the developmental process of many inflammatory, infectious, and autoimmune diseases and functions to kill or inhibit tumor cells, increase the phagocytic activity of neutrophils, and stimulate the production of other cytokines." (PMID 23735240, 2013). "Occasionally, some patients may develop AIH after starting anti-TNF-α therapy for autoimmune disorders." (PMID 24082887, 2013). "As TNF signaling links the innate and adaptive immune systems, it could help to explain the involvement of both systems in autoimmune diseases." (PMID 23555688, 2013). "TNF-α also plays a central role in the pathology of autoimmune disease." (PMID 23055830, 2012). "Physicians using TNF-α inhibitors in the treatment of various rheumatic and autoimmune diseases should be aware of the potential for the development of glycemic disturbance in these patients, a side effect that may be underpublicized." (PMID 22234148, 2012). "Our findings are consistent with trials showing BCG vaccination decreased disease activity and prevented progression of brain lesions in advanced multiple sclerosis, an autoimmune disease similarly sharing autoreactive T cells vulnerable to TNF-triggered cell death." (PMID 22905105, 2012). "Decreased levels of proinflammatory cytokines IL-6, IL-12 and TNF-α do not easily explain the symptoms of autoimmune diseases observed in DC-STAMP-deficient mice." (PMID 21978263, 2011). "Several studies have established that TNF is important in immune responses against mycobacterial infections but it is also a central mediator of pathology in autoimmune diseases." (PMID 22132068, 2011). "TNFα-induced protein 3(TNFAIP3) is a key regulator of inflammation and immunityinvolved in the development of various autoimmune diseases and it also desensitizescells from TNFα-induced cytotoxicity and was shown to be anti-apoptotic inbreast cancer MCF7S1 cells." (PMID 21637860, 2011). "Intriguingly, various biological compounds targeting TNF resulted effective in RA treatment, while detrimental in multiple sclerosis, indicating that TNF related pathways may play a dual role in autoimmune diseases." (PMID 21533026, 2011). "Some reports have also suggested that BV may be an efficient treatment for multiple sclerosis (MS) and other autoimmune diseases based on the inhibition of TNF-α production." (PMID 20950451, 2010). "The pro-inflammatory activities link TNF-alpha with a wide variety of autoimmune diseases." (PMID 27713252, 2010). "Immune regulation by TNFα has been observed in other models of autoimmune diseases as well." (PMID 18380898, 2008). "The occurrence of ‘revertant’ mice was an exciting phenomenon since TNFα could not only reduce the frequency of autoimmune disease but also abrogate the actual ongoing autoimmune process at a time when its clinical features were already obvious." (PMID 23675028, 2007). "As per the generally-accepted mechanism for the pathogenesis of autoimmune diseases, naive T cells upon activation by antigen produce IL-2 and then undergo clonal expansion and produce pro-inflammatory cytokines (tumor necrosis factor, TNF)." (PMID 16759382, 2006).